MC1R (melanocortin 1 receptor)
Diseases named in the same sentence as MC1R in open-access papers (continued):
Sharing a sentence is not in itself a finding about the gene and the disease.
cutaneous melanoma (continued). "Further factors are MC1R genetic polymorphism, and perhaps other yet ill-defined environmental factors, but some MC1R variants are associated with increased risk of cutaneous melanoma regardless of skin type and hair colour." (PMID 26850723, 2016). "Most, but not all, previous studies have shown that MC1R variants are associated with an increased risk of both cutaneous melanoma and nonmelanoma skin cancers." (PMID 14612910, 2003). "Interestingly, MC1R polymorphic variants, particularly co-presence of multiple MC1R variants and red hair color variants, may increase the penetrance of CDKN2A mutations and the risk of cutaneous melanoma in affected families." (PMID 38474338, 2024). "MC1R genotype has been shown to have a persisting effect on risk of cutaneous melanoma and nonmelanoma skin cancer even after adjusting for hair and skin colour, which supports the notion that MC1R may directly modulate melanocyte growth and differentiation." (PMID 14612910, 2003). "Therefore, it is possible to hypothesize that specific genotypes, including the TERT –245T>C polymorphism, besides the debated SNPS in MC1R (not confirmed by the present study), may influence the occurrence of somatic BRAF mutations in individuals who develop cutaneous melanoma." (PMID 29464027, 2018).
metastatic melanoma (23 papers, 2002 to 2026). A melanoma that has spread from its primary site to another anatomic site. "A limitation of this study is the relatively small number of patients, and larger‐scale studies from different populations on germline MC1R variants as a predictive marker for ICIs in metastatic melanoma are warranted." (PMID 40926353, 2025). "In a previous study, a poorer efficacy of BRAF inhibitors was observed in metastatic melanoma patients with germline MC1R variants (R), possibly related to altered p38 MAP kinase phosphorylation." (PMID 40926353, 2025). "We aimed to address whether inherited polymorphisms in MC1R impact the efficacy of immune checkpoint inhibitors (ICI) in patients with metastatic melanoma." (PMID 40926353, 2025). "A theranostic approach involving lead-based radioligands was evaluated for MC1R-expressing metastatic melanoma patients." (PMID 41510167, 2026). "Univariate and multivariate analysis on the effect of MC1R R germline variants on progression‐free survival and overall survival in ICI‐treated patients with metastatic melanoma by Cox proportional hazards regression model." (PMID 40926353, 2025). "Melanocortin-1 receptor (MC1R) is a promising target for radionuclide therapy of metastatic melanoma, and alpha-melanocyte stimulating hormone (α-MSH) peptide analogs show high affinities to MC1Rs." (PMID 39828865, 2025). "Elevated MC1R protein expression correlated with worse OS in both primary (p = 0.0031) and metastatic melanoma (p = 0.0034)." (PMID 40981345, 2025). "As an analog of alpha-melanocortin stimulating hormone (α-MSH), MC1L binds with melanocortin receptor 1 (MC1R) overexpressed in metastatic melanoma." (PMID 38095674, 2024). "Some studies have shown that the overexpressed of MC1R involves greater than 80% of melanotic and amelanotic human metastatic melanoma." (PMID 39519055, 2024). "In previous studies, we had aimed at similar enhancements to a peptide construct targeted to the melanocortin receptor subtype 1 (MC1R) in metastatic melanoma." (PMID 37955792, 2024). "Clinical and pathological parameters were compared to continuous MC1R intensity scores in both the primary and metastatic melanoma cohorts using analysis of variance." (PMID 37790306, 2023). "A significant correlation between MC1R variants and worse outcomes (overall response rate and progression-free survival) in BRAF-mutated metastatic melanoma patients treated with target therapy was observed, due to the interactions of MC1R with other pathways." (PMID 34356109, 2021). "Here, for the first time, we determine the antitumor potential of tomatine, a mixture of α-tomatine and dehydrotomatine, in metastatic melanoma (MM) cell lines harboring different BRAF and MC1R variants." (PMID 32718103, 2020). "More than 80% of human metastatic melanoma cell lines were found expression of Mc1r, and there have high levels in primary and metastatic melanoma tissue samples through immunohistochemistry analyses." (PMID 32117457, 2020). "Persistent inhibition of MC1R provided a significant survival advantage resulting in part from slower tumor growth, establishing MC1R as a compelling new molecular target for metastatic melanoma." (PMID 27028866, 2016). "Immunohistochemistry revealed a strong expression of melanocortin 1 receptor in all tested primary and metastatic melanomas, but also demonstrated low levels of expression in adrenal medulla, cerebellum, liver and keratinocytes." (PMID 12177778, 2002). "MC1R variants may also impact treatment outcomes: metastatic melanoma patients with concurrent BRAF V600 mutations and MC1R variants experienced lower response rates and shorter PFS on BRAF inhibitor therapy." (PMID 40981345, 2025).
metastatic melanoma (continued). "These MC1R-directed radioligands could enable both imaging (with 68Ga, 64Cu, 89Zr etc.)and therapy (with 177Lu, 225Ac, 161Tb) of metastatic melanoma." (PMID 41008677, 2025). "[225Ac]Ac–crown–αMSH was developed containing a chelator with a tetraazacrown-6 backbone with four pendant acetate side arms, which is connected to a peptide to target the melanocortin 1 receptor (MC1R) in specifically expressed primary and metastatic melanoma." (PMID 38256909, 2024). "Collectively, these data suggest that targeting MC1R could serve as an approach in the treatment of metastatic melanoma." (PMID 37608347, 2023). "Additionally, in metastatic melanoma both MC1R and α-MSH have been reported to be overexpressed at levels much higher than normal cells." (PMID 37608347, 2023). "Also, all metastatic melanomas (n=11) stained strongly positive for MC1R, including metastasis in lymph nodes, maxilla, intestine, while the adjacent normal tissues, including the epidermis, dermis, appendages, and subcutaneous tissue and connective tissues, were negative." (PMID 12177778, 2002). "Melanocortin-1 receptor (MC1R) is the primary target for α-MSH binding and is found to be significantly overexpressed on primary and metastatic melanoma in comparison to the levels observed in normal cells." (PMID 38708130, 2024). "They further synthesized 225Ac-crown-αMSH, with a peptide targeting the melanocortin 1 receptor (MC1R), specifically expressed in primary and metastatic melanoma." (PMID 37376167, 2023). "Another MC1R targeting peptide, [203Pb]Pb-DOTA-GGNle-CycMSHhex demonstrated a favorable accumulation and good imaging properties in both immunocompetent subcutaneous B16/F1 and B16/F10 mouse models, as well as in a B16/F10 pulmonary metastatic melanoma mouse model 116​." (PMID 41510167, 2026).
vitiligo (21 papers, 2010 to 2025). Generalized well circumscribed patches of leukoderma that are generally distributed over symmetric body locations and is due to autoimmune destruction of melanocytes. "Of note, previous GWASs of vitiligo have identified rs9926296 and rs4268748 as susceptibility variants, and both SNPs were mapped to MC1R, which was finally reported as a vitiligo-associated gene." (PMID 33679896, 2021). "We determined that MC1R was not only a vitiligo risk genetic locus but also was targeted by Isorhamnetin and Kaempferide." (PMID 29145845, 2017). "In addition, the MC1R is also implicated in vitiligo, a pigmentation disorder characterized by the loss or destruction of melanocytes in the skin and hair follicles." (PMID 37569558, 2023). "However, another study shows that the Arg160Trp allele of MC1R gene may be able to protect against vitiligo." (PMID 26870082, 2016). "Researchers propose that these findings support the MC1R agonist hydrogel as a promising treatment for vitiligo." (PMID 37569558, 2023). "Genome-wide association studies (GWAS) have identified more than 50 genetic risk variants for vitiligo, including genes related to cytolysis (GZMB, CTLA4, FOXP3) and melanocyte function (TYR, MC1R, XBP1)." (PMID 36182982, 2022). "MC1R regulates the quality and quantity of melanin production and minor vitiligo autoantigen, and upon activation switches to eumelanin production." (PMID 29771307, 2018). "Further study need to be conducted to confirm this conclusion between vitiligo and MC1R coding region SNPs." (PMID 26870082, 2016). "MC1R, encoding the receptor protein for melanocyte-stimulating hormone (MSH), is a regulator of melanogenesis and minor vitiligo autoantigen, associating with malignant melanoma and with skin and hair color." (PMID 26870082, 2016). "Dersimelagon is currently in the clinical approval phase for this orphan disease, and as a non‐peptide MC1R agonist, could also be used in future clinical studies on patients with vitiligo." (PMID 40788636, 2025). "Such MC1R agonists might be particularly suitable for vitiligo patients with darker skin phototypes." (PMID 40788636, 2025). "The expression of both POMC and MC1‐R were significantly lower in the lesional skin, compared with both the non‐lesional skin of vitiligo cases, as well as compared with the controls, while they were significantly higher in non‐lesional vitiligo skin than in controls." (PMID 37275429, 2023). "Thus, MC1R emerges as a potential therapeutic target for vitiligo since MC1R plays a crucial role in regulating skin pigmentation." (PMID 37569558, 2023). "However, previous studied did not consider methylation modification, and our study shows that the methylation levels of key genes involved in these important regulatory processes, such as TYP1, IL17, and MC1R, are altered in vitiligo melanocyte PIG3V." (PMID 33790887, 2021). "As a key regulator of skin pigmentation, MC1R may be an effective therapeutic target for vitiligo." (PMID 37569558, 2023). "Thus, exogenous supplementation of MC1R agonist is a possible therapeutic strategy for vitiligo." (PMID 36359263, 2022). "As expected, the expression of MC1R, TYR, TYRP1, and DCT was significantly downregulated during vitiligo pathogenesis." (PMID 38159176, 2024). "This emphasizes the need for potent and highly selective MC1R agonists, distinct from α-MSH, to effectively treat vitiligo." (PMID 37569558, 2023). "Relative expression of melanogenesis-related genes MC1R, MITF, tyrosinase, TRP1, and TRP2 varied with age group, line of chicken, visual acuity, and vitiligo status." (PMID 35547230, 2022). "Expression shows MC1R is marked significantly different between lesional and non-lesional vitiligo skin." (PMID 26870082, 2016). "Of note, augmented melanocortin 1 receptor (MC1R) expression in the nonlesional skin of vitiligo patients compared with controls may represent an attempt to restore normal pigmentation when the ligand is barely produced." (PMID 41007740, 2025).
vitiligo (continued). "At the same time, increased MC1R expression on melanocytes membrane in the nonlesional skin of vitiligo patients matching to controls may represent an attempt to restore normal pigmentation." (PMID 36359263, 2022).
albinism (12 papers, 2011 to 2025). A congenital disorder characterized by partial or complete absence of melanin pigment in the eyes, hair, or skin. "For example, in Astyanax mexicanus, albinism and depigmentation in cavefish are linked to oculocutaneous albinism type 2 (oca2) and melanocortin receptor 1 (mc1r), respectively." (PMID 40709436, 2025). "Indeed, two Mendelian pigment phenotypes (albinism and brown) are both widespread, highly penetrant, and mediated through loss-of-function mutations in the genes Oca2 and Mc1r, respectively." (PMID 27363593, 2016). "Whereas the absence of melanin is traditionally considered as one character state, albinism, irrespective of the underlying genetic basis, we propose here to distinguish OCA2-associated albinism from Mc1R-associated albinism, or from albinism associated with any other gene." (PMID 26042146, 2015). "Molecular genetic diagnosis for most patients started with a next-generation sequencing (NGS) panel targeting genes associated with albinism—TYR, OCA2, MC1R, MITF, SLC45A2, TYRP1, and GPR143—as the initial clinical diagnosis for all patients was albinism." (PMID 39457042, 2024). "This study aimed to identify single-nucleotide polymorphisms (SNPs) in the coding region of MC1R and exons 2 and 3 of KIT associated with coat color abnormalities (white-spotting and albinism) in Bali cattle using direct sequencing." (PMID 37577199, 2023). "The MC1R gene and cytochrome oxidase subunit I gene within mitochondria have been used to identify abnormalities in coat color, including white-spotting and albinism, in Bali cattle." (PMID 37577199, 2023). "Moreover, our findings highlighted a possible involvement of MC1R in the occurrence of albinism." (PMID 27776349, 2017). "Various genes, including ASIP (agouti), TYR (albinism), TYRP1 (brown), KIT (dominant white), KITLG (roan), PMEL (dilution), melanocortin 1 receptor (MC1R) (extension), and MITF (white-spotted), have been identified as important pigmentation genes underlying coat color variation." (PMID 37577199, 2023). "In addition to ASIP, IRF4, KITLG, MC1R, SLC24A4, and TYRP1, we chose 41 additional candidate genes with a potential role in human skin color based on their phenotypes in model organisms, or in humans affected with albinism." (PMID 23555287, 2013).
Obesity (12 papers, 2011 to 2025). Accumulation of substantial excess body fat. "Mc1re/e mice with global MC1R deficiency showed normal weight development under chow-fed conditions and in diet-induced obesity, but significant increases in liver weight, plasma TG concentration and WAT depot weights." (PMID 39117851, 2024). "Hepatocyte-specific loss of MC1R disturbs fatty acid metabolism in the liver and leads to an obesity phenotype characterized by enhanced adipocyte hypertrophy and TG accumulation in the liver and circulation." (PMID 39117851, 2024). "Cigarette smoking, obesity and MC1R variants are associated with different measures of periorbital ageing." (PMID 21787368, 2011). "In summary, male sex, sun exposure, smoking, obesity and MC1R variants were associated with measures of cutaneous ageing." (PMID 21787368, 2011). "Here, we aimed to study whether global MC1R deficiency renders mice susceptible for enhanced fat accumulation and obesity." (PMID 39117851, 2024). "Indeed, mice with hepatocyte-specific loss of MC1R recapitulated the obesity phenotype as evidenced by increased white adipose tissue mass and liver weight, and elevated triglyceride accumulation in the liver and circulation." (PMID 39117851, 2024). "Thus, we hypothesized that the obesity phenotype is driven by MC1R deficiency in hepatocytes." (PMID 39117851, 2024). "The role of MRAP2 in melanin signaling is unclear, but loss-of-function MRAP2 variants are associated with obesity, which also involves α-MSH, Mc1R, and MC4R signaling." (PMID 34436011, 2021). "In contrast, MC1R deficiency in the liver does not lead to obesity or diabetes, but it likely enhances DNL and promotes fibrosis, apoptosis and inflammation, which in turn, predisposes to the development of NAFLD." (PMID 39117851, 2024). "Interestingly, earlier studies have found that MC1R is present in human and mouse adipocytes, and upregulated in the adipose tissue of subjects with obesity." (PMID 39117851, 2024). "Agouti/ASIP is a high affinity antagonist on MC1R and increased ectopic expression of this protein is associated phenotypically with yellow fur (mice), late onset obesity, hyperphagia, increased growth and non-insulin dependent diabetes." (PMID 26459134, 2015). "Expression of MC1R, MC4R and MC5R has been suggested in the adipose tissue of human obese subjects and these receptors may reflect an aspect of the pathophysiology of human obesity." (PMID 26459134, 2015).
nevus (10 papers, 2012 to 2025). Nevus (or naevus, plural nevi or naevi, from nævus, Latin for "birthmark") is the medical term for sharply circumscribed[1] and chronic lesions of the skin or mucosa. "In detail, MC1R RHC variants carriers have a peculiar nevus phenotype, dermoscopically characterized by reduced structures and lower prevalence of atypical pigment network, visible vessels, dots and globules, and eccentric hyperpigmentation, associated with a high degree of skin freckling." (PMID 34356109, 2021). "Regarding cutaneous nevi, significant associations were identified between the IRF4 gene (P = 4.19 × 10−14) and the MC1R gene (P = 8.64 × 10−4), also as previously published." (PMID 40261663, 2025). "Additionally, as revealed by clinical and daily routine non-invasive dermoscopy of nevi, MC1R status has an impact on nevus phenotype and RCM features." (PMID 34356109, 2021). "Model F added MC1R genotype and measures of indoor and outdoor UV exposure to Model A. We also assessed the predictive ability of these models in subgroups stratified by mole phenotype (e.g. nevus-resistant (“none” and “few” moles) and nevus-prone (“some” and “many” moles))." (PMID 25003831, 2014).
Parkinson disease (9 papers, 2019 to 2025). A progressive degenerative disorder of the central nervous system characterized by loss of dopamine producing neurons in the substantia nigra and the presence of Lewy bodies in the substantia nigra and locus coeruleus. "The dysfunction of the MC1R gene has been shown to significantly worsen the severity of dopaminergic neurodegeneration in the SN associated with Parkinson’s disease." (PMID 39796093, 2024). "Recent findings have revealed that melanocortin 1 receptor (MC1R) deficiency leads to Parkinson’s disease-like dopaminergic neurodegeneration in the substantia nigra (SN)." (PMID 39796093, 2024). "Melanocortin 1 receptor (MC1R) is a key pigmentation gene, and loss-of-function of MC1R variants that produce red hair may be associated with Parkinson’s disease (PD)." (PMID 38110615, 2023). "MC1R is found in both the peripheral and CNS, implying that both the peripheral and central forms of MC1R might potentially impact dopaminergic neurons in Parkinson’s disease." (PMID 38110615, 2023).
non-melanoma skin carcinoma (8 papers, 2008 to 2025). "MC1R, encoding for α-MSH receptor 1, is a well-known genetic determinant of MM and non-melanoma skin cancer risk." (PMID 40004203, 2025). "Based on improvement to the AUC, the final selected models for both the self-reported and physician-measured models included MC1R, nevi and non-melanoma skin cancer, in addition to demographic factors." (PMID 24134749, 2013).